HMGN2P18 (high mobility group nucleosomal binding domain 2 pseudogene 18)
Gene: Processed pseudogene on chromosome 1 (155,148,544 to 155,148,813, forward strand). Ensembl gene ENSG00000223452.
Diseases named in the same sentence as HMGN2P18 in open-access papers:
HMGN2P18 is named in the same sentence as 2 diseases in open-access papers, as found by Europe PMC text mining. Sharing a sentence is not in itself a finding about the gene and the disease. The quoted sentences say what the papers report.
infection (1 paper, 2024). The state of being infected such as from the introduction of a foreign agent such as serum, vaccine, antigenic substance or organism. "Additionally, we identified 10 genomic regions associated with breakthrough infection (SLC6A20, ST6GAL1, MUC16, FUT6, MXI1, MUC4, HMGN2P18-KRTCAP2, NFKBIZ and APOC1), and one with breakthrough severity (APOE)." (PMID 39384777, 2024).
tumour (1 paper, 2016). "The expression of only one gene (HMGN2P18) was confounded by tumour anatomical location." (PMID 29263803, 2016).